IGF1R (insulin like growth factor 1 receptor)
Diseases named in the same sentence as IGF1R in open-access papers (continued):
Sharing a sentence is not in itself a finding about the gene and the disease.
tumor (continued). "These in vivo results confirmed that IGF-1r silencing can increase the radiation sensitivity of ESCC tumors in this established tumor model." (PMID 25363593, 2014). "In this study, we predicted IGF1R to be a target of miR-143 and miR-145, which are a cluster of miRNAs that have been reported in many studies to be downregulated and to function as tumor suppressors in most cancers." (PMID 25474488, 2014). "Itfunctions as a tumor suppressor by directly targeting several positive regulators ofcell cycle progression that have been implicated in tumorigenesis, including SRF,Igf1R, ADAM 17, ADAM10, cyclin G1, Wnt1, Bcl-w and PI3CG." (PMID 25012758, 2014). "Binding of IGF-1 to receptor IGF1R activates the pathway and enhances tumor development by stimulating cell proliferation and inhibiting apoptosis." (PMID 25006674, 2014). "So, it is possible that expression of IGF-1R by the tumor cells in HL can be an effect of malignant transformation or due to differentiation towards plasma cells." (PMID 24489919, 2014). "We first sorted aRMS tumor cells for Pdgfra or Igf1r positivity versus negativity, then performed DNA content analysis." (PMID 24453992, 2014). "Our results demonstrate that tumor stromal cells contribute in the physiopathological response to IGF-1/IGF-1R." (PMID 25095896, 2014). "Our results support previous studies indicating that IGF1R positivity reflects a well differentiated tumor with low metastatic capacity." (PMID 25362932, 2014). "In this study, miR-223 was shown to directly bind to IGF-1R and repress IGF-1 signaling cascade including AKT/mTOR/p70S6K suggesting that miR-223 functions as tumor suppressor through the suppression of IGF-1R-mediated cell growth signaling." (PMID 25628647, 2014). "In the present case, the mRNA expression of both IGF1 and IGF2 has increased (FDR = 4.65E-35 and FDR = 3.46E-15, respectively); however, the expression of IGF1R remained the same in the tumour tissue compared to that in the control tissue." (PMID 25496518, 2014). "Using in vivo xenograft model, we confirmed that glucosamine prohibits primary tumor growth through reducing IGF-1R signalling and increasing ER-stress." (PMID 24438088, 2014). "During differentiation or tumor progression, miR-223 suppresses cell proliferation by targeting insulin-like growth factor-1 receptor (IGF1R)." (PMID 24708646, 2014). "Tumor response to anti-IGF1R therapy has only been published for a total of 7 patients with OS, and 4 of these patients had stable disease reported for at least 3 months after initiation of treatment." (PMID 25170759, 2014). "Inhibition of tumor growth in vivo has been achieved with anti-IGF-1R antibodies, anti-ligand antibodies, receptor-specific tyrosine kinase inhibitors, and agents such as the cyclolignan picropodophyllin (PPP)." (PMID 25268741, 2014). "PDAC tumor tissues at various stages showed increased expression of IGF-1R compared with normal pancreas tissues." (PMID 24809702, 2014). "Upregulation of IGF-1R in human PDAC tissues has been reported and associates with higher tumor grade and poor survival." (PMID 24667580, 2014). "PC3 cells have been previously established in a CAM assay, so we investigated the effects of changes in IGF1R/INSR levels on tumor growth and vessel density using PC3 PCa cells." (PMID 24809298, 2014). "Transfections for transient IGF1R/INSR overexpression or downregulation were performed once prior placing the tumor cells on the CAM." (PMID 24809298, 2014). "This study is the first study to use primary clinical tumor material to provide a novel comprehensive insight into the relation between the IGF-1R signaling pathway and EOC tumorigenesis." (PMID 24103397, 2013). "The IR therefore supports tumour cell proliferation of several cell types independently of the IGF1R, and we have here extended these observations to NSCLC cells." (PMID 23826179, 2013). "The one SDHB-positive WT tumor expressed IGF1R at comparable levels to the mutant GISTs in the study." (PMID 23730622, 2013).
tumor (continued). "OSI-906 (Astellas Pharma) is a potent, selective, and orally bioavailable dual IGF-1R/IR kinase inhibitor which has demonstrated in vivo efficacy in tumor models and is currently in clinical testing." (PMID 23525758, 2013). "A variety of fully human anti-IGF-1R monoclonal antibodies have been characterized and showed strong anti-tumor activity in vitro and in vivo." (PMID 23525758, 2013). "To test the effects of inhibiting IGF-IR activation on tumor cell viability, we treated NB7, NB10, and NB16 cells with BMS 754807, a small molecule inhibitor of the insulin-like growth factor 1 receptor/insulin receptor family kinases." (PMID 24349301, 2013). "In oesophageal squamous cell carcinoma, miR-375 was found to negatively regulate IGF-1R expression to inhibit cell migration, colony formation, and tumor size." (PMID 24051403, 2013). "Successful inhibition of tumor growth was subsequently demonstrated in ES xenograft models with dominant negative receptors, antisense knockdown, and small molecules targeting IGF-1R." (PMID 23431249, 2013). "An important factor in support of targeting IGF-1R in ES is that EWS-FLI1 acts to suppress transcription of IGFBP3 in tumor cells, thereby resulting in higher levels of circulating IGF-1 and thus increasing activation of the IGF-1R pathway." (PMID 23431249, 2013). "The IGF1R pathway acts on several biological mechanisms that promote tumor progression – mitogenesis, protection from apoptosis, malignant transformation, and metastasis." (PMID 23688189, 2013). "Between 5% and 100% of cells in each tumor sample were positive for IGF-1R when previously assessed by immunohistochemistry." (PMID 23431249, 2013). "IGF-1R is highly expressed in both ES cell lines and patient tumor samples and inhibition of the IGF-1R signaling resulted in profoundly reduced cell migratory ability and increased anoikis-induced apoptosis in several ES cell lines." (PMID 24062983, 2013). "The results we have obtained with ganitumab and irinotecan using the COLO 205 tumor model are consistent with this therapeutic concept and show that IGF1R inhibition is compatible with cell cycle (S-phase) inhibition." (PMID 23383308, 2013). "Pre-clinical studies have demonstrated that dalotuzumab acts by inhibiting IGF-1- and IGF-2-mediated tumor cell proliferation, IGF-1R autophosphorylation, and Akt phosphorylation." (PMID 23525758, 2013). "IGF-1R is highly expressed by ES cells, and many studies have demonstrated the importance of the IGF-1R pathway in ES tumor models." (PMID 23761859, 2013). "In conclusion, whereas ganitumab therapy modestly affected 22Rv1 tumor growth, combining IGF-1R blockade with calorie restriction resulted in a significant decrease in final tumor weight and improved metabolic profile." (PMID 23823800, 2013). "These investigators reported that the insulin like growth factor receptor 1 (IGF-1R), a candidate mediator of the tumor-promoting effect of obesity, is expressed specifically in BCACs." (PMID 23560112, 2013). "Inhibition of the IGF1R using inhibitory antibodies results in a considerable reduction in proliferation of tumour cell lines and it has been found to be overactive in cancers including prostate, breast, colon and gallbladder carcinoma." (PMID 23826179, 2013). "Consistent with the established role of IGF1 in supporting tumour cell proliferation, neutralising antibody-directed blockade of the IGF1-R in each of the NSCLC cell lines tested resulted in a partial inhibition of proliferation." (PMID 23826179, 2013). "In contrast, tumor formation was noted in three of four mice at week 9 or three of three mice by week 15 after injection of sh-Luc transduced IGF-1R+ BC0145 or IGF-1Rhi BC0244 cells, respectively." (PMID 23663564, 2013). "The in vivo studies of co-inhibition of EGFR and IGF-1R on the anti-tumor effect of radiotherapy were determined in a nu/nu MDA-MB-468 xenograft mouse model." (PMID 23777562, 2013).
tumor (continued). "Taken together, the results presented indicate that in NSCLC cells with a high IR:IGF1R ratio the IR contributes to driving tumour cell proliferation and that a small molecule IR/IGF1R inhibitor is a more effective approach to inhibiting cell proliferation." (PMID 23826179, 2013). "Consistent with this idea, tumor cell apoptosis was increased by stable expression of a myristoylated IGF1R C-terminus or by introduction of a synthetic 17-aminoacid peptide from the C-terminus." (PMID 22778948, 2012). "We found that the increased PAPPA secretion in tumor tissues is accompanied predominantly by activation of IGF1R-Akt signaling pathway." (PMID 23152806, 2012). "Our results in the group of patients in earlier stages who received trastuzumab as adjuvant/neoadjuvant therapy demonstrated that those having tumours with IGF1R overexpression and inactive Bad had shorter PFS." (PMID 22454081, 2012). "MVP overexpression (those tumours with moderate or strong expression of the protein) was related to insulin-like growth factor receptor-1 (IGF-1R) expression (P = 0.014)." (PMID 22931894, 2012). "The formation of hybrid receptors of the IGF-1R has also been shown to contribute to tumor growth as shown in several in vitro tumor models, including breast carcinoma cell lines." (PMID 22348393, 2012). "Tumor IGF-1R and IGF-2 mRNA expression were clearly elevated in 48 paired samples as demonstrated in tissues from four representative patients." (PMID 22159423, 2012). "In case of triple-negative cancer cells (MDA-MB 231), tumor progression is controlled by modulating IGF-1R." (PMID 22485142, 2012). "IGF-1R blockage using different approaches leads to dramatic reductions in proliferation and other neoplasia parameters." (PMID 22485142, 2012). "The regulatory effects of MSM on tumorigenesis and tumor progression were studied by examining STAT5b/IGF-1R." (PMID 22485142, 2012). "This review highlights the most relevant clinical data emphasizing the main tumor types where IGF-1R inhibition showed potential interest." (PMID 22415797, 2012). "Taken together, our results demonstrate that miR-122 functions as a tumor suppressor and plays an important role in inhibiting the tumorigenesis through targeting IGF1R and regulating PI3K/Akt/mTOR/p70S6K pathway." (PMID 23056576, 2012). "Unfortunately, the median duration of EW response was only 5–7 months, probably because tumour cells escape IGF-1R inhibition, through AKT or through activation of other signalling pathways (e.g., other TK receptors, mTOR)." (PMID 23226965, 2012). "Insulin like growth factor receptor—1 (IGF-1R) is a transmembrane receptor with tyrosine kinase activity found to be over-expressed in many tumor types." (PMID 22415797, 2012). "In fact, we found IGF1R overexpression in 25% of the tumours, especially in those of early stage patients who developed recurrences." (PMID 22454081, 2012). "We tested our rationale for combined inhibition of the Src and IGF-1R pathways by determining the effects on growth and apoptosis then signal transduction, followed by effects on tumor growth in several relevant animal models." (PMID 23300537, 2012). "The antiapoptotic and mitogenic function of IGF2 is mediated by IGF-1R, and the expression of this receptor has been also demonstrated in SS cell lines and tumor specimens bearing SS18-SSX1 and SS18-SSX2 fusion proteins." (PMID 22550415, 2012). "MVP and IGF-1R expression were related in OCSCC tumours and conferred reduced long-term survival in patients suffering advanced stages of the disease." (PMID 22931894, 2012). "Patients receiving adjuvant trastuzumab with α-IGF1R or pBad overexpressing tumours presented shorter progression-free survival (PFS) (all P⩽0.043)." (PMID 22454081, 2012). "Ets-1 is a potential transcription factor to IGF1R, and it is involved in tumour invasion and metastasis processes also regulated by syndecan-2 in HT-1080 cells." (PMID 22745764, 2012).
tumor (continued). "Using NCI data, we confirmed that 29 of the 90 potential inhibitors of IGF1R and 12 of the 17 specific inhibitors of IGF1R showed growth inhibition effects on many human tumor cell lines." (PMID 23242155, 2012). "For example, mir-145, a known tumor-suppressor-miRNA, was shown to inhibit the IGF1R axis by targeting both IRS-1 and IGF1R." (PMID 22747855, 2012). "17-AAG induces in vitro apoptosis and in vivo tumour growth retardation in OS as a single agent and in combination with cisplatin and restores the efficacy of the IGF1R inhibitor and imatinib in EW models." (PMID 23226965, 2012). "IGF-1R has also been recently shown to translocate to the nucleus of human tumor cells in a ligand-dependent manner." (PMID 22879999, 2012). "In vitro studies with a number of these agents have demonstrated inhibition of IGF-1R, high level of growth inhibition, survival reduction, complete pathway blockade, and xenograft tumor growth reduction." (PMID 21647361, 2011). "We propose the combination of tyrosine-kinase inhibitors with endocytosis inhibitors as a new therapeutic approach to achieve a stronger degree of receptor inhibition in this, or other neoplasms dependent on IGF1R signaling." (PMID 21611203, 2011). "As therapeutic strategies for co-targeting IGF1R and IR-A move forward in clinical development, evaluating IR-A levels in clinical tumor samples becomes critical for identifying the most appropriate population to receive IGF-targeted therapy." (PMID 22046260, 2011). "In patient 2, upregulation of mTOR was seen in the primary tumor, perhaps explaining the initial response to the IGF1R and mTOR inhibitor combination, while the resistant tumor that emerged showed activation of the ERK pathway as well." (PMID 21494688, 2011). "In patient 2, constitutive activation of Akt and mTOR is similar to that in patient 1's recurrent tumor, and is seen in baseline pre-treatment tumor and in tumor that was resistant to IGF1R and mTOR combination treatment." (PMID 21494688, 2011). "Animal models have shown decreased tumor growth after IGF1R inactivation and with decreased circulating or tissue levels of IGF1." (PMID 21696633, 2011). "In the tumor tissues at xenograft nude mice, the expression of IGF-1R was also suppressed in miR-223 group as compared with EV group." (PMID 22073238, 2011). "In this model, miR-223 targeted IGF-1R and its downstream signal pathway, which exerted a major function in tumor cell growth regulation." (PMID 22073238, 2011). "Similar to the IGF-1R involvement in tumor development, studies involving the insulinreceptors indicated a connection between insulin receptors and cancer." (PMID 23908801, 2011). "The IGF-1R is commonly expressed by neoplastic cell lines and human cancers and on circulating tumor cells." (PMID 21696633, 2011). "In summary, all these studies indicate that insulin, IGF-1, IGF-2, and their signalingvia the IR and IGF-1R can induce tumor growth." (PMID 23908801, 2011). "In animal models with transformed tumors where IGF-1R was overexpressed, strategies that caused IGF-1R downregulation such as antisense against IGF-1R produced profound tumor apoptosis and massive reductions of metastases." (PMID 21729319, 2011). "This is further supported by evidence that tumor cells utilize IGF-1R signaling as a survival mechanism that renders them independent of EGF signals." (PMID 21464922, 2011). "IGF-1R and insulin receptor interaction has been seen in many human tumor cell lines after the appearance of IGF-1R monoclonal antibodies." (PMID 21729319, 2011). "Sections of tumor before IGF1R antibody therapy and after IGF1R antibody combined with mTOR inhibitor therapy were available for analysis." (PMID 21494688, 2011). "The activity of insulin-like growth factor 1 receptor (IGF1R) is essential for tumour development and progression through the signaling of antiapoptotic and prosurvival pathways." (PMID 21197471, 2011).
tumor (continued). "This is based on evidence that IGF-1R signalling protects tumour cells from many insults, including chemotherapeutic agents and ionizing radiation, thus limiting the efficacy of such therapy." (PMID 21647361, 2011). "IGF1R isover-expressed by many tumour cell lines and targeted disruption of the IGF1Rgene can abolish cell transformation." (PMID 21479216, 2011). "The role of IGF-2R in IGF axis appears to serve as a site for IGF-2 clearance, therefore reduces the availability of a potent ligand for IGF-1R, the major gateway for carcinogenesis, tumor growth and proliferation." (PMID 21729319, 2011). "Increased occurrence of these hybrids can be observed in several tumor cells as the result of IR and/or IGF1R overexpression." (PMID 22046260, 2011). "Such ability was demonstrated in several human tumor cell lines, where phosphorylated IGF-1R and its downstream proteins, including ERK and p70s6k were all effectively inhibited by OSI-906 (OSI)." (PMID 21729319, 2011). "Different strategies applied to inhibit IGF-1R expression or function have resulted in blocking tumor growth and metastasis and have enhanced sensitivity to cytostatic drugs and irradiation." (PMID 21423728, 2011). "(d) Although IGF1R was reported to be overexpressed in a variety of cancers, in some tumours the IGF signal exerts a protective effect against tumour formation and inhibits the emergence of an aggressive tumour phenotype." (PMID 20924377, 2010). "A-928605 is an optimized pyrazolopyrimidine that has previously been reported to have an IGF1R in vitro enzymatic IC50 of 37 nM as well as an IC50 value of 90 nM for inhibition of cellular IGF1R phosphorylation induced by IGF1 in A431 tumor cells." (PMID 19732452, 2009). "IGF1R has both mitogenic and antiapoptotic roles in tumor development via signaling through the phosphatidylinositol-3-kinase and mitogen-activated protein kinase pathways, with its adaptor protein IRS1 critical in activating the downstream pathways." (PMID 19843326, 2009). "IGF-1R expression was mostly localized to tumor cells showing partial to complete strong membranous localization with weaker cytoplasmic localization and tumor cell heterogeneity seen." (PMID 19806209, 2009). "It is important in future studies to include anti-IGF1R antibodies, such as A12, which recognise both human and mouse IGF1R, to examine the tumour-to-background signal ratio from regions of interest in tumour and normal tissue." (PMID 19491901, 2009). "As a direct comparison, equal amounts of AVE-1642-conjugated Alexa 680 (0.1 nmol) were injected into mice carrying R-/IGF1R xenograft tumours." (PMID 19491901, 2009). "Mice carrying R-/IGF1R tumours were pretreated with AVE-1642 antibody for 2 days before the injection of AVE-1642-conjugated Alexa 680, which efficiently downregulates IGF1R levels in tumours." (PMID 19491901, 2009). "Our results suggest that small-molecule fluorophores, such as Alexa 680, are more suitable for in vivo tumour imaging to identify IGF1R expression and its downregulation." (PMID 19491901, 2009). "These IGF1R specific antibodies show clear inhibition of tumor growth in numerous pre-clinical tumor models." (PMID 19732452, 2009). "We show that both antibody-conjugated Alexa 680, and QDs, localised to xenograft tumours that express IGF1R." (PMID 19491901, 2009). "The tumours with diminished IGF1R levels showed a dramatically decreased fluorescence, compared with the tumours with a regular amount of IGF1R level." (PMID 19491901, 2009). "This compound was found to be selective when analyzed in a panel of in vitro kinase assays, followed by profiling in vivo with a novel IGF1R driven tumor model." (PMID 19732452, 2009). "The tumor cell microenvironment appears to govern the ability of IGF-1R to enhance or inhibit the pro-apoptotic activity of TNFα." (PMID 19784388, 2008).